PLA2G2D (phospholipase A2 group IID)
Description:
Secretory calcium-dependent phospholipase A2 that primarily targets extracellular lipids, exerting anti-inflammatory and immunosuppressive functions. Hydrolyzes the ester bond of the fatty acyl group attached at sn-2 position of phospholipids (phospholipase A2 activity) with preference for phosphatidylethanolamines and phosphatidylglycerols over phosphatidylcholines. In draining lymph nodes, selectively hydrolyzes diacyl and alkenyl forms of phosphatidylethanolamines, releasing omega-3 polyunsaturated fatty acids (PUFAs) such as eicosapentaenoate and docosahexaenoate that are precursors of the anti-inflammatory lipid mediators, resolvins (By similarity). During the resolution phase of acute inflammation drives docosahexaenoate-derived resolvin D1 synthesis, which suppresses dendritic cell activation and T-helper 1 immune response (By similarity). May act in an autocrine and paracrine manner (By similarity). Via a mechanism independent of its catalytic activity, promotes differentiation of regulatory T cells (Tregs) and participates in the maintenance of immune tolerance (By similarity). May contribute to lipid remodeling of cellular membranes and generation of lipid mediators involved in pathogen clearance. Displays bactericidal activity against Gram-positive bacteria by directly hydrolyzing phospholipids of the bacterial membrane (By similarity).
Synonyms: sPLA2-IID; SPLASH; sPLA2S; PLA2IID
Tractability: Small molecule: a high-quality ligand is known; it belongs to a druggable protein family. Antibody: UniProt places it where antibodies can reach, with high confidence; its Gene Ontology location is reachable by antibodies, with high confidence; UniProt predicts a signal peptide or a membrane-spanning region. PROTAC: a small molecule that binds it is known.
Target class: Enzyme; Hydrolase
Gene: Protein-coding gene on chromosome 1 (20,111,939 to 20,119,566, reverse strand). Ensembl gene ENSG00000117215.
Subcellular location: Secreted
Pathways (Reactome):
Metabolism: Acyl chain remodelling of PC; Acyl chain remodelling of PE; Acyl chain remodelling of PG; Acyl chain remodelling of PI; Acyl chain remodelling of PS; Synthesis of PA
Gene Ontology:
Molecular function: phospholipase A2 activity; calcium ion binding; phospholipid binding; heparan sulfate proteoglycan binding; heparin binding
Biological process: phosphatidylcholine metabolic process; inflammatory response; negative regulation of T cell proliferation; phosphatidylethanolamine metabolic process; phosphatidylglycerol metabolic process; phospholipid metabolic process; regulation of acute inflammatory response to antigenic stimulus; arachidonate secretion; lipid catabolic process
Cellular component: extracellular region
Genetic constraint (gnomAD): Loss-of-function variants: 16 observed, 11.58 expected, observed/expected ratio (o/e) 1.38, 90% interval 0.92 to 1.89. The upper end of that interval is the gene's LOEUF score, 1.89, which puts it in group 6 of 6, group 1 being the genes least tolerant of losing a copy. Missense variants: 164 observed, 161.68 expected, observed/expected ratio (o/e) 1.01, 90% interval 0.89 to 1.15. Synonymous variants: 75 observed, 64.17 expected, observed/expected ratio (o/e) 1.17, 90% interval 0.97 to 1.42.
Homologues: Orthologues: chimpanzee PLA2G2D (99% identical), macaque PLA2G2D (88% identical), rabbit PLA2G2D (79% identical), pig PLA2G2D (76% identical), dog PLA2G2D (75% identical), guinea pig PLA2G2D (71% identical), mouse Pla2g2d (71% identical), rat Pla2g2d (70% identical), Caenorhabditis elegans C07E3.9 (27% identical), Caenorhabditis elegans C03H5.4 (26% identical). Paralogues in human: PLA2G2A (47% identical), PLA2G2F (44% identical), PLA2G5 (41% identical), PLA2G10 (39% identical), PLA2G2E (37% identical), PLA2G1B (34% identical), PLA2G2C (31% identical), OC90 (29% identical).
Diseases named in the same sentence as PLA2G2D in open-access papers:
PLA2G2D is named in the same sentence as 72 diseases in open-access papers, as found by Europe PMC text mining. Sharing a sentence is not in itself a finding about the gene and the disease. The quoted sentences say what the papers report.
Obesity (11 papers, 2016 to 2025). Accumulation of substantial excess body fat. "Pla2g2d, a member of the sPLA2 family, significantly reduced in obese patients and mice, and is negatively correlated with obesity and insulin resistance." (PMID 39627688, 2024). "PLA2G2D increased energy expenditure and thermogenesis by facilitating adipocyte browning, thereby ameliorating diet-induced obesity and WAT inflammation." (PMID 38836117, 2024). "As for the genes involved in lipid metabolism, Pla2g2d, Lipo3, and Naaa were significantly upregulated, promoting anabolism, while lipid-transport-related genes, such as Abcg5, Apo3, and Stard5, were down-regulated, leading to lipid surplus and diverse metabolic syndromes, such as obesity." (PMID 39007149, 2024). "A higher expression of PLA2G2D, PLA2G4A and PLA2G7 were found in scWAT of individuals living with healthy obesity." (PMID 38024342, 2023).
breast carcinoma (10 papers, 2013 to 2024). "In addition, upregulation of PLA2G2D improves the prognosis of cutaneous melanoma, breast cancer, and head and neck squamous cell carcinoma." (PMID 38022687, 2023). "However, PLA2G2D expression was also found to be positively correlated with immune infiltration and better prognosis in head and neck squamous cell carcinoma and breast cancer in human, which is consistent with our current findings in CSCC." (PMID 34733790, 2021). "Of note, the small molecule drug targeted by PLA2G2D mepacrine (also named as quinacrine), which was originally used as an anti-malarial drug has been recently repurposed as an anticancer agent in treating ovarian cancer, gynecologic, breast cancer, and colon cancer." (PMID 37210507, 2023). "However, the expression of PLA2G2D has also been found to be positively correlated with better prognosis in human HNSCC and breast cancer, which is also consistent with the result of our survival analysis." (PMID 35844514, 2022).
melanoma (7 papers, 2021 to 2024). A malignant, usually aggressive tumor composed of atypical, neoplastic melanocytes. "To predict the prognosis of melanoma patients, we calculated the risk score of each patient based on the expression and corresponding lambda value of seven genes (PLA2G2D, FUT8, PLA2G4E, PLA2G5, PLA2G1B, B3GNT2, and ST3GAL5)." (PMID 37205993, 2023). "Moreover, we also found that the high expression levels of CXCL13, FCRLA, MS4A1, and PLA2G2D were positively associated with the better response of melanoma patients treated with anti-PD1 and anti-CTLA4." (PMID 34395521, 2021). "Our results showed that the CXCL13, FCRLA, MS4A1, and PLA2G2D were positively correlated with the level of CTL infiltration in the melanoma patients treated with anti-PD-L1 or anti-CTLA4." (PMID 34395521, 2021). "Finally, we directly examined the predictive value of PLA2G2D expression for patient response to ICB therapy in melanoma and urothelial carcinoma immunotherapy cohorts, given the lack of transcriptional data in CSCC immunotherapy cohorts." (PMID 34733790, 2021). "Furthermore, in the urothelial carcinoma anti-PDL1 therapy cohort, the percentage of CR/PR patients was higher in PLA2G2D-high patients, which is similar to that in melanoma immunotherapy cohort." (PMID 34733790, 2021). "To validate the relationship between PLA2G2D and the response to ICB treatment, we analyzed the transcriptome data from immunotherapy cohorts of melanoma and urothelial carcinoma." (PMID 34733790, 2021). "In the melanoma anti-PD1 therapy cohort, we selected patients who have not previously received immunotherapy for enrollment analysis and divided them based on PLA2G2D expression at pretreatment stage." (PMID 34733790, 2021).
skin cancer (6 papers, 2018 to 2023). "However, PLA2G2D expression is associated with delayed tumor growth by enhancing anti-tumor immunity in a mouse model of skin cancer." (PMID 36199579, 2022).
psoriasis (5 papers, 2018 to 2023). An autoimmune condition characterized by red, well-delineated plaques with silvery scales that are usually on the extensor surfaces and scalp. "In fact, despite the low expression of sPLA2-IID in the skin, Pla2g2d deficiency leads to exacerbation of CHS and psoriasis, likely because sPLA2-IID attenuates adaptive immunity in the LNs, thereby sequestering pathogenic Th1 and Th17 immune responses." (PMID 37189415, 2023). "Despite the low expression of sPLA2-IID in skin, Pla2g2d deficiency leads to exacerbation of CHS and psoriasis." (PMID 30546811, 2018).
cervical squamous cell carcinoma (4 papers, 2021 to 2025). A squamous cell carcinoma arising from the cervical epithelium. "Additionally, PLA2G2D is an immune- and metabolism-associated molecule identified as a biomarker to predict the prognosis of cervical squamous cell carcinoma." (PMID 40066453, 2025).
Insulin resistance (4 papers, 2016 to 2024). Increased resistance towards insulin, that is, diminished effectiveness of insulin in reducing blood glucose levels. "In vitro and in vivo studies demonstrated that Pdpn+ macrophages alleviated insulin resistance and modulated adipokine/cytokine expression in adipocytes via the Pla2g2d-DHA/EPA-GPR120 pathway." (PMID 39627688, 2024). "Moreover, we discovered a novel Pdpn+ macrophage subset that ameliorated insulin resistance in adipocytes and exerted anti-inflammatory and vascular protective effects through the Pla2g2d-DHA/EPA-GPR120 axis." (PMID 39627688, 2024).
cervical cancer (3 papers, 2021 to 2025). A primary or metastatic malignant neoplasm involving the cervix. "In contrast, a positive correlation between immune infiltration and PLA2G2D expression has been identified in cervical cancer." (PMID 38022687, 2023).
viral infection (3 papers, 2021 to 2023). "The high expression of PLA2G2D increases viral infection, and mice lacking PLAG2D are protected from COVID-19 invasion." (PMID 35774129, 2022).
colorectal cancer (2 papers, 2008 to 2021). A primary or metastatic malignant neoplasm that affects the colon or rectum. "As a member of sPLA2, group IID PLA2 (encoded by PLA2G2D), is broadly expressed in human body, such as the spleen, lymph nodes, squamous epithelium, and colorectal cancer tissue." (PMID 34733790, 2021). "Interestingly, the PLA2G2A, PLA2G2C, PLA2G2D, PLA2G2E, PLA2G2F and PLA2G5 genes reside within the same region of human chromosome 1 at p35–36.1, a region frequently altered in colorectal cancer." (PMID 18212756, 2008).
lung disease (2 papers, 2008 to 2023). "However further studies are required to demonstrate the role of PLA2G2D in lung diseases." (PMID 37048117, 2023).
non-small cell lung carcinoma (2 papers, 2024). A group of at least three distinct histological types of lung cancer, including non-small cell squamous cell carcinoma, adenocarcinoma, and large cell carcinoma. "Nevertheless, PLA2G2D is also reported to plays a key role in non-small cell lung cancer angiogenesis through aerobic glycolysis." (PMID 39239507, 2024). "PLA2G2A and PLA2G2D are two types of sPLA2 enzymes that have gained great attention for their involvement in cancer angiogenesis and metastasis in lung adenocarcinoma and in non-small cell lung cancer (NSCLC), respectively." (PMID 39596471, 2024).
ovarian carcinoma (2 papers, 2021 to 2023). A malignant neoplasm originating from the surface ovarian epithelium. "In our study, we combined TMB and TIME evaluation methods to identify a set of genes related to the immune status of ovarian cancer, including CXCL13, FCRLA, MS4A1, and PLA2G2D." (PMID 34395521, 2021).
allergic bronchopulmonary aspergillosis (1 paper, 2025). Allergic bronchopulmonary aspergillosis (ABPA) is a rare immunologic pulmonary disorder caused by hypersensitivity to Aspergillus fumigatus, clinically manifesting with poorly controlled asthma and recurrent pulmonary infiltrates. "Studies have found high expression of Pla2g4c, Pla2g2c, Pla2g2d, and Pla2g5 in a mouse model of ABPA (allergic bronchopulmonary aspergillosis)." (PMID 40278587, 2025).
colon adenocarcinoma (1 paper, 2008). "Interestingly, we observed marked alterations in the expression levels of PLA2G2D, PLA2G5 and PLA2G3 in colon adenocarcinomas." (PMID 18212756, 2008).
gram-positive bacterial infections (1 paper, 2021). Infections caused by bacteria that retain the crystal violet stain (positive) when treated by the gram-staining method. "Pla2g2d also known as the “resolving sPLA2” ameliorates inflammation through mobilizing proresolving lipid mediators and reducing Th1 cytokine production, while Pla2g2a can be stimulated by IL-6 production and protects against Gram-positive bacterial infection." (PMID 34295313, 2021).
lung adenocarcinoma (1 paper, 2026). A carcinoma that arises from the lung and is characterized by the presence of malignant glandular epithelial cells. "Some of these genes (HMGA2, MMP13, BIRC7, and PLA2G2D) have been reported to be overexpressed in various cancers, including lung adenocarcinoma, and are associated with tumor progression and metastasis, supporting their potential as biomarkers for PD-1 immunotherapy." (PMID 41529246, 2026).
lymphoma (1 paper, 2022). A malignant (clonal) proliferation of B- lymphocytes or T- lymphocytes which involves the lymph nodes, bone marrow and/or extranodal sites. "We reported that down-regulation of CHIT1, SIGLEC15, PLA2G2D and TMEM163 was associated with poor prognosis in immunocompetent NHL, and expression levels of four genes were lower in lymphoma than in normal tissues." (PMID 36249005, 2022). "However, high expression of PLA2G2D exists in lymphatic tissue itself, and the difference in expression between EBV+ and EBV- lymphoma patients may be masked by PLA2G2D expressed in tissue itself." (PMID 36249005, 2022). "Four differential genes between EBV+ and EBV- lymphoma patients were screened out with the significance of the survival and prognosis of lymphoma, including CHIT1, SIGLEC15, PLA2G2D and TMEM163." (PMID 36249005, 2022). "The role of M0, M2 macrophages in tumor immune microenvironment is consistent with the favorable genes of CHIT1, SIGLEC15, PLA2G2D and TMEM163 for the prognosis of lymphoma patients." (PMID 36249005, 2022).
primary immunodeficiency (1 paper, 2021). "Interestingly, CXCL13, FCRLA, and PLA2G2D were also associated with primary immunodeficiency." (PMID 34395521, 2021).
pterygium (1 paper, 2022). A wedge-shaped fibrovascular lesion arising from the bulbar conjunctiva and extending to the cornea. "In active pterygium, genes involved with immune and inflammatory response (CXCL9 and PLA2G2D), angiogenesis (SERPINB5 and BM4), keratinization (DSG1), response to UV light (TYR) and negative regulation of apoptotic process (PIM1) are up regulated in relation to atrophic pterygium." (PMID 34997134, 2022).
pulmonary arterial hypertension (1 paper, 2023). Pulmonary arterial hypertension (PAH) is a group of diseases characterized by mean pulmonary artery pressure >20 mmHg and elevated pulmonary arterial resistance leading to right heart failure. "A genome RNA expression profiling study had shown upregulation of PLA2G12A in addition to PLA2G1B and PLA2G2D in patients with pulmonary arterial hypertension secondary to IPF." (PMID 37048117, 2023).
rectum adenocarcinoma (1 paper, 2021). An adenocarcinoma arising from the rectum. "Recently, PLA2G2D was identified as one of the high-risk genes for colorectal and rectum adenocarcinoma that were negatively correlated with patient survival." (PMID 34733790, 2021).
cancer (27 papers, 2008 to 2026). A tumor composed of atypical neoplastic, often pleomorphic cells that invade other tissues. "The upregulation of PLA2G2D has been associated with increased glucose uptake, ATP production, and lactate production, all of which are characteristic features of aerobic glycolysis in cancer cells." (PMID 39596471, 2024). "While the bulk of current literature has characterized the role of Pla2g2d in fatty-acid metabolism within the contexts of autoimmune disorders and viral infections, little is known of its relevance in cancer development and immunotherapy response." (PMID 34446728, 2021). "It has been shown that PLA2G2D is silenced due to an upregulation of the glycolytic pathway, a fact that could inhibit aerobic glycolysis in cancer cells." (PMID 39596471, 2024). "The cancer-promoting effect of PLA2G2D has also been suggested in human." (PMID 34733790, 2021). "The role of Pla2g2d in cancer has been investigated as well." (PMID 34733790, 2021). "This suggests that PLA2G2D may drive angiogenesis by promoting glycolysis in cancer cells." (PMID 39596471, 2024). "Besides, it has been reported that upregulation of PLA2G2D could be a potential biomarker for cancer immunotherapy." (PMID 35774129, 2022). "More importantly, CD8+ TILs were the only cell population that were more frequently found inside the tumor region in PLA2G2D high-expressed samples, suggesting that PLA2G2D could participate in the recruitment of CD8+ TILs into the cancer nests, either directly or indirectly." (PMID 34733790, 2021). "Indeed, database analysis revealed PLA2g2d to be highly expressed by DLBCL tissues compared to paired-healthy tissues, whereas this was not the case for any other form of cancer." (PMID 36100608, 2022).